STAT1 (signal transducer and activator of transcription 1)
Diseases named in the same sentence as STAT1 in open-access papers (continued):
Sharing a sentence is not in itself a finding about the gene and the disease.
cervical carcinoma (34 papers, 2010 to 2025). A carcinoma arising from either the exocervical squamous epithelium or the endocervical glandular epithelium. "In conclusion, silencing of STAT1 caused metabolic imbalance and recovered the Warburg effect in Fra-1–overexpressing cervical cancer cells." (PMID 33102485, 2020). "We found that Fra-1 overexpression in cervical cancer cells caused very significant changes in STAT1 expression at both the protein and mRNA levels." (PMID 33102485, 2020). "We recently demonstrated that, in cervical cancer cells, STAT1 (Signal Transducer and Activator of Transcription) controls PARP1 levels, also interacting with STAT3." (PMID 37190289, 2023). "In cervical tissues, overexpression of STAT1 mRNA and protein have been reported in cervical cancer samples compared to normal cervical tissues." (PMID 37372319, 2023). "For example, STAT1 can affect the development of cervical cancer by regulating the expression of PARP1." (PMID 36911390, 2023). "Firstly, we started by considering the role of STAT1 in cervical cancer, especially in cervical lesions." (PMID 35163748, 2022). "Together our results demonstrated that silencing of STAT1 impaired the inhibitory effect of Fra-1 on cervical cancer cell growth." (PMID 33102485, 2020). "We also investigated the effects of STAT1 on metabolic reprogramming of cervical cancer cells overexpressing Fra-1." (PMID 33102485, 2020). "Silencing of STAT1 impaired the inhibitory effect of Fra-1 on cervical cancer cell growth, while knock-down of STAT1 reversed the effect on cell senescence and mitochondrial dysfunction caused by Fra-1 in HeLa cells." (PMID 33102485, 2020). "We next explored STAT1 silencing affected the expression of senescence-related molecules in cervical cancer cells." (PMID 33102485, 2020). "In summary, our results showed that Fra-1 inhibited cervical cancer cell growth and repaired metabolic dysfunction via STAT1, and these effects involved the Warburg effect and fatty acid metabolism in cervical cancer cells." (PMID 33102485, 2020). "Regarding the role of STAT1 in cervical cancer, its expression in cervical lesions and cervical cancer has been elucidated." (PMID 33076315, 2020). "As shown in the regulatory network, TFs STAT1 and FOXP3 were involved in regulatory relationship with multiple IRGs for cervical cancer, while IRGs PGR and LTA were associated with multiple TFs for endometrial cancer." (PMID 32793281, 2020). "Silencing of STAT1 restored the proliferation of cervical cancer cells and the growth of xenograft tumors to some extent." (PMID 33102485, 2020). "To investigate a putative role of ANXA2, NDRG1 and STAT1 on radiation/drug-mediated killing of tumor cells, we set up in vitro experiments using radiosensitive (C-4I) or radioresistant (CaSki) cervical cancer cells." (PMID 31242951, 2019). "In HPV-associated cervical cancers, patients with normal or upregulated STAT1 expression often present with higher-grade lesions, yet they exhibit longer overall survival compared to those patients with STAT1−/−." (PMID 38675812, 2024). "Notably, we recently demonstrated that, in cervical cancer cells, STAT1 controls PARP1 levels through multiple mechanisms, possibly involving also STAT3." (PMID 37190289, 2023). "Some studies show that the expression of STAT1 is essential for the induction of death in tumor cells, and its higher levels in cervical cancer samples compared to resistant cases suggest that STAT1 may contribute to improved radiosensitivity." (PMID 35163748, 2022).
cervical carcinoma (continued). "In addition, a STAT1 inhibitor (Fludarabine) blocked IFN-γ-induced PD-L1 expression in cervical cancer cells, further confirming that PRMT5 regulated PD-L1 expression through STAT1." (PMID 34522232, 2021). "In this study, we firstly uncovered that PRMT5 knockdown in cervical cancer cells decreased PD-L1 expression by regulating the transcription of STAT1 gene through symmetric dimethylation of histone H3R2, and increased the number and function of T cells in the tumor microenvironment." (PMID 34522232, 2021). "Because we found that Fra-1 inhibited HeLa cell proliferation and up-regulated STAT1 expression, we investigated whether silencing STAT1 using siRNAs designed specifically for STAT1 could alter the inhibitory effect of Fra-1 on cervical cancer cell growth." (PMID 33102485, 2020). "Silencing of STAT1 also recovered metabolic reprogramming in cervical cancer cells." (PMID 33102485, 2020). "Finally, we confirmed that the inhibition of cell growth and the Warburg effect in cervical cancer cells by Fra-1 is mediated via STAT1." (PMID 33102485, 2020). "In our another paper that has been published recently, we have clarified that E6 protein induced by HPV16/18 could significantly promoted the ubiquitination and degradation of KPNA1 that resulted in the suppression of nuclear transport of phosphorylated STAT1 and apoptosis in cervical cancer cells." (PMID 35991835, 2022). "Therefore, we explored whether the transcription factor STAT1 is involved in the effects of Fra-1 in cervical cancer cells." (PMID 33102485, 2020). "By co-culturing a cervical cancer cell line with P. bivia, we confirmed that three out of the ten top predicted genes in the transkingdom network (lysosomal associated membrane protein 3 (LAMP3), STAT1, TAP1), all regulators of immunological pathways, were upregulated by this microorganism." (PMID 30294508, 2018). "The analysis showed that OAS2, KLHDC7B, STAT1, TYMP, PSME2 and GBP5 were significantly upregulated in cervical cancer cells compared with normal epithelial cells." (PMID 40259929, 2025). "P. bivia has been shown to upregulate proinflammatory (LAMP3, STAT1, and TAP1) genes in cervical cancer." (PMID 35928983, 2022). "The expression of STAT1 is related to the increase of human papillomavirus (HPV) 16 viral load and the survival rate of cervical cancer." (PMID 35928229, 2022). "Mechanistically, PRMT5 enhanced the transcription of STAT1 through symmetric dimethylation of histone H3R2 and thus promoted PD-L1 expression in cervical cancer cells." (PMID 34522232, 2021). "In a study on cervical cancer, the importance of IFN-inducible activation of STAT1 and STAT2 was demonstrated through the use of STAT1 and STAT2 knockout human HeLa cells, yet the STAT3 knockout did not have any effect on ISGs." (PMID 33329603, 2020). "Available evidence for its role in cervical cancer suggests that during the early stage of HPV infection, STAT1 expression is suppressed and viral replication is activated with evasion of the immune surveillance." (PMID 31242951, 2019). "STAT1/IRF-1 pathways initiated by IFNγ had been shown to be important in TNFα and IFNγ synergism in inducing cervical cancer cell apoptosis." (PMID 27342639, 2016). "The effect of V protein variants on components of the interferon-stimulated gene factor 3 (ISGF3), STAT1 and STAT2 proteins were experimentally tested in cervical carcinoma cell lines." (PMID 20937132, 2010).
cervical carcinoma (continued). "EPOR is expressed in cervical cancer, and the binding of erythropoietin (Epo) to its receptor induced cell proliferation; such cell response was related to the activation of JAK2, JAK3, STAT3, and STAT5, but not JAK1 and STAT1 in cervical cancer." (PMID 37372319, 2023). "Here, we demonstrated a critical role for IFN-γ/STAT1/STAT3 signaling in regulating PARP1 levels in HGSOC cells, in line with our recent results in cervical cancer, and with the emerging evidence on the functional interplay between the STATs signaling cascade and PARP1." (PMID 37190289, 2023). "Significantly higher levels of STAT1 are observed in cervical cancer samples compared to other nontumor tissues." (PMID 35163748, 2022). "Collectively, these findings suggested that STAT1 expression affected by PRMT5-mediated epigenetic regulation could drive PD-L1 expression, which promoted the development of cervical cancer." (PMID 34522232, 2021). "We also noticed STAT1 blocking reagent Fludarabine could prevent PD-L1 expression of cervical cancer cells induced by IFN-γ, thus proving PRMT5 did regulate PD-L1 expression depending on STAT1." (PMID 34522232, 2021). "Our results revealed that STAT1 silencing recovered the ROS level in Fra-1–overexpressing cervical cancer cells and reduced the NAD+/NADH ratio, which increased the metabolic instability of the cervical cancer cells." (PMID 33102485, 2020). "The upregulation of STAT1 mediated by interferon epsilon (IFNE) was described on cervical cancer cells, but to our knowledge, there are no studies describing the role of IFNE in CC." (PMID 23865481, 2013). "We recently demonstrated that in cervical cancer cells (HPV-positive CaSki and C-4I), a perturbation in the balanced expression/activation of STAT1 and STAT3 might improve the efficacy of DNA-damaging treatments, at least partially, by lowering PARP1 levels in tumors." (PMID 37190289, 2023).
multiple myeloma (30 papers, 2008 to 2025). "We also demonstrate that myeloma cells upregulate the expression of CIITA in osteocytes through TP/2DDR-mediated STAT1/IRF1 signaling." (PMID 35760800, 2022). "It is reported that BMSCs-derived EVs suppress immune function in multiple myeloma by activating MDSCs through the STAT3/STAT1 signaling pathway, thereby promoting the development of multiple myeloma." (PMID 36439438, 2022). "The formation of a trimer complex among myeloma cell integrin α6, laminin 8, and EGFR on MSCs activates the Akt, ERK, STAT1/3 signaling pathways, and therefore upregulates osteolytic cytokine expression in both myeloma cells and MSCs." (PMID 34150666, 2021). "Myeloma cells are endowed with acquired cross-resistance to doxorubicin and radiation when they have an over-expression of STAT1 mRNA and protein levels." (PMID 34522170, 2021). "To determine the impact of those signaling pathways on MSC cytokine expression, we added the inhibitor targeting ERK1/2, STAT1, or Akt to cocultures of MSCs and myeloma cells." (PMID 34150666, 2021). "Atorvastatin was demonstrated to inhibit phosphorylation of STAT1 imposed by IFNγ in mononuclear cells of multiple myeloma patients; hence, we were convinced to find its effect on PD-L1 expression in HepG2 cells in this study." (PMID 34445462, 2021). "Upon stimulation with IFNg, STAT1 activation resulted in PD-L1 upregulation and in reduction of NK-cell activity against tumor cells in multiple myeloma, acute myeloid leukemia (AML), and acute lymphoblastic leukemia (ALL)." (PMID 29765155, 2018). "IFN-α is known to phosphorylate Stat1 on the Ser727 residue in human U266 myeloma and human fibroblast cell line." (PMID 22435755, 2012). "Specifically, Stat1 is constitutively phosphorylated at Y701 in many blood tumors including multiple myeloma, erythroleukemia and acute myelogenous leukemia (AML)." (PMID 18941537, 2008). "It has been reported that STAT1 is the crucial driver of increased glycolysis in myeloma cells." (PMID 38764020, 2024). "Implicit in these results is that targeting the integrin αv/STAT1/CIITA signaling pathways could be a potential strategy for the treatment of myeloma-induced bone disease." (PMID 35760800, 2022). "Interestingly, we only discovered a small network of proteins consistent across all eight myeloma subgroups, highlighted by the over-expression of STAT1, TCF3 and interferon alpha." (PMID 33572851, 2021). "Similarly, STAT1 inhibition led to decreased PD-L1 levels in myeloma cells and thus suppressed the antitumor function of cytotoxic T cells." (PMID 29765155, 2018). "While it was known that IFN-γ via STAT1 could increase HLA-E levels, we here indisputably prove that CREB1 and STAT1 both contribute to HLA-E expression in myeloma, with CREB1 binding to HLA-E promoter and CREB1 inhibitors decreasing HLA-E expression in cell lines and patient samples." (PMID 38902472, 2024). "Moreover, we found in a multiple myeloma mouse model that exosomes derived from bone marrow stromal cells or multiple myeloma cells themselves could activate both the STAT1 and STAT3 pathway leading to expansion and increased suppressive activity of the MDSCs." (PMID 27029037, 2016). "Because IFN-γ robustly induces PD-L1 in myeloma plasma cells, reduced PTPRG would be expected to prolong/augment STAT1 signaling and enhance PD-L1 induction, whereas higher PTPRG should blunt this response." (PMID 41050668, 2025). "Knockdown of integrin α6 in myeloma cells nearly diminished the activation effect from myeloma cells on the phosphorylation of ERK1/2, STAT1, and Akt in MSCs, except STAT3." (PMID 34150666, 2021). "Our findings indicate that myeloma cells upregulate cytokine expression in MSCs via the integrin α6-activated ERK1/2, Akt, and STAT1 signaling pathways." (PMID 34150666, 2021).
multiple myeloma (continued). "An early study in multiple myeloma cells showed that IFN‐γ promoted PD‐L1 expression through a MyD88‐, TRAF6‐ and MEK‐dependent pathway, and IFN‐γ activated transcription factor STAT1 partially via the MEK/ERK pathway." (PMID 28218497, 2017). "In multiple myeloma cell lines, the pan-HDACi panobinostat has demonstrated the capacity to markedly upregulate PD-L1 by enhancing STAT1 expression in the presence of IFN-γ, while the HDAC6-selective inhibitor A452 was shown to induce PD-L1 upregulation in multiple myeloma cells in vitro." (PMID 38672128, 2024). "In turn, myeloma cell–secreted 2-deoxy-D-ribose, the product of thymidine catalyzed by the function of thymidine phosphorylase, upregulates CIITA expression in osteocytes through the STAT1/IRF1 signaling pathway." (PMID 35760800, 2022). "Our results show that myeloma cell integrin α6 binds to laminin 8 and epidermal growth factor receptor (EGFR) on MSCs, forms a trimer complex, activates the ERK1/2, STAT1/3, PI3K/Akt signaling pathways, enhances the secretion of osteolytic cytokines from myeloma cells and MSCs." (PMID 34150666, 2021). "When we added the inhibitor specific for ERK1/2, STAT1, STAT3, or Akt to cocultures of myeloma cells and MSCs, we found that the kinase inhibitor alone or in combination reduced the expression of CXCL1, CXCL2, SDF1, and MCP1 in myeloma cells." (PMID 34150666, 2021). "As we found that STAT1C-induced apoptosis in ESCC correlates with the down-regulation of several pro-survival proteins such as BCL-2 and BCL-xL, previous studies also have shown that STAT1 can promote apoptosis by down-regulating BCL-2 and BCL-xL in multiple myelomas." (PMID 25355139, 2014). "In addition, STAT1, a classical transcription factor that participates in the JAK/STAT pathway or cascades with the RIG1, NF-kappaB, and IRF signaling pathways, has been reported to mediate tumor immunity in multiple myeloma." (PMID 40524208, 2025). "Phosphorylation and nuclear localization of STAT1 in response to IL-6 is comparable in CD45+ and CD45- myeloma cells, indicating that CD45 does not regulate STAT1 phosphorylation." (PMID 25781885, 2015). "Interestingly, the phosphorylation level of STAT3 but not STAT1 in CD45+ cells was significantly higher compared to that of CD45- cells, while the phosphorylation level of ERK in CD45+ myeloma cells was relatively low." (PMID 25781885, 2015). "SAR317461, a small molecule inhibitor of JAK2 identified by structure-based drug design, was used as it has been shown to potently down-regulate expression of phosphorylated JAK2 and STAT1 without affecting expression of total JAK2 and STAT1 in multiple myeloma cell lines." (PMID 22697788, 2012).
rheumatoid arthritis (29 papers, 2006 to 2025). A chronic, systemic autoimmune disorder characterized by inflammation in the synovial membranes and articular surfaces. "Confirming the relevance of these results, STAT1 mRNA expression was also decreased in Tn from SpA patients, as compared with healthy controls and rheumatoid arthritis patients." (PMID 37920469, 2023). "Upregulation of CALR, PRDM1, STAT1, TAGAP and TNRC6B has been associated elsewhere with adult rheumatoid arthritis or juvenile polyarticular arthritis." (PMID 24000795, 2013). "The therapeutic efficacy of a synthetic decoy oligodeoxynucleotide (ODN) binding and neutralizing STAT-1 was tested in murine antigen-induced arthritis (AIA) as a model for human rheumatoid arthritis (RA)." (PMID 16507120, 2006). "E2F2 directly regulates the STAT1 and PI3K/AKT/NF-κB pathways to exacerbate the inflammatory phenotype in rheumatoid arthritis synovial fibroblasts and mouse embryonic fibroblasts." (PMID 40508152, 2025). "Taken together, DF blocked the JAK/STAT signaling pathway by inhibiting STAT1 and STAT3 phosphorylation, which clarified the important role of JAK/STAT signaling pathway in anti-rheumatoid arthritis." (PMID 36386123, 2022). "Transcription factors STAT1 and STAT2 are activated by interferons and are common targets in studies of potential therapeutics for OA and rheumatoid arthritis." (PMID 35299636, 2022). "STAT1 and STAT6 have been reported to be increasingly expressed in rheumatoid arthritis, wherein they mediate the secretion of inflammatory mediators." (PMID 32290603, 2020). "In that study, PBMC samples from patients with rheumatoid arthritis had been stimulated with type I and type II IFN, while untreated samples and TNFα-stimulated samples were used as STAT1/2 pathway inactive controls." (PMID 33193365, 2020). "This is in line with published data from fibroblast-like synoviocytes isolated from patients with rheumatoid arthritis and stimulated with recombinant OSM, in which OSM increased STAT1, STAT3 and STAT5 expression." (PMID 24710357, 2014).